TNFAIP3 (TNF alpha induced protein 3)
Diseases named in the same sentence as TNFAIP3 in open-access papers (continued):
Sharing a sentence is not in itself a finding about the gene and the disease.
Glucose intolerance (1 paper, 2023). Glucose intolerance (GI) can be defined as dysglycemia that comprises both prediabetes and diabetes. "Maintenance of glucose tolerance required Rela but was independent of classical NF-κB inflammatory cascades, as blocking NF-κB signalling in vivo by beta cell knockout of Ikbkg (NEMO), or beta cell overexpression of Tnfaip3 (A20), did not cause severe glucose intolerance." (PMID 37311878, 2023).
gout (1 paper, 2023). A condition characterized by painful swelling of the joints, which is caused by deposition of urate crystals. "The CD4+ TCs and CD8+ TCs from gout remission were enriched in chemokines, such as CXCR4, as well as various antiinflammatory regulators (TNFAIP3, ZFP36, and SMAD7; an antagonist of TGF-β signaling)." (PMID 38063198, 2023).
heart failure (1 paper, 2024). Inability of the heart to pump blood at an adequate rate to meet tissue metabolic requirements. "In the GSE57338 dataset (one heart failure dataset), both OTUD1 and TNFAIP3 were upregulated." (PMID 39309432, 2024).
Hepatitis (1 paper, 2021). Inflammation of the liver. "Finally, we identified an induction of antiapoptotic genes such as Tnfaip3 known to promote survival in both hepatic IRI and ConA-induced hepatitis models." (PMID 33824326, 2021).
Hydrocephalus (1 paper, 2020). Hydrocephalus is an active distension of the ventricular system of the brain resulting from inadequate passage of CSF from its point of production within the cerebral ventricles to its point of absorption into the systemic circulation. "Our findings showed that rh-relaxin-2 attenuated degranulation of mast cells and neuroinflammation, improved neurological outcomes, and ameliorated hydrocephalus after GMH through RXFP1/PI3K-AKT/TNFAIP3/NF-κB signaling pathway." (PMID 32859236, 2020).
idiopathic inflammatory myopathies (1 paper, 2014). "Single-nucleotide polymorphisms (SNPs) in the TNFAIP3, IFIH1, and IRF5 genes have been associated with several auto-inflammation diseases, while the susceptibility between these genes and idiopathic inflammatory myopathies (IIMs) were not reported." (PMID 25337792, 2014).
infarction (1 paper, 2020). A localised pathological necrosis of tissue resulting from obstruction of the blood supply usually by a thrombus, an embolus, or vascular torsion. "TNFAIP3 encodes an anti-inflammatory protein whose overexpression in the heart was shown to attenuate myocardial hypertrophic response and post-infarction remodeling and inflammation in transgenic mouse models, improving cardiac function." (PMID 31924244, 2020).
Infertility (1 paper, 2022). "The transplant studies showing rescue of the I325N ovarian phenotype when placed in wild type hosts support an extrinsic mechanism whereby loss of LH secretion associating with CNS inflammation is sufficient for driving infertility in Tnfaip3 I325N mice." (PMID 35464428, 2022).
influenza infection (1 paper, 2013). "The role of TNF and TNFAIP3 in inflammation is well known, and TNFAIP3 has been shown previously to play a specific role in influenza infection." (PMID 23935999, 2013).
insomnia (1 paper, 2025). A sleep disorder characterized by difficulty in falling asleep and/or remaining asleep. "LASSO regression identified 1 common diagnostic biomarker gene for COPD and insomnia, namely TNFAIP3." (PMID 41155519, 2025). "In summary, TNFAIP3 and Berbamine hold significant research value in the treatment of insomnia associated with COPD." (PMID 41155519, 2025). "Functional studies of TNFAIP3 in COPD with insomnia reveal its potential role in regulating inflammatory responses." (PMID 41155519, 2025). "Future research should further elucidate the specific mechanisms of TNFAIP3 in COPD with insomnia, aiming to provide more precise targets for clinical interventions." (PMID 41155519, 2025). "Our findings underscore the potential of TNFAIP3-targeted strategies in mitigating COPD–insomnia comorbidity, particularly in the elderly, who are often underrepresented in mechanistic studies yet overrepresented in clinical prevalence." (PMID 41155519, 2025). "Considering the relationship between systemic oxidative burden and poor sleep quality, TNFAIP3-targeted antioxidants could disrupt the ROS–inflammation–insomnia cycle." (PMID 41155519, 2025). "In summary, Berbamine may influence the co-morbid mechanisms of COPD and insomnia by regulating the expression or function of TNFAIP3." (PMID 41155519, 2025). "Through its ubiquitin-editing activity, TNFAIP3 modulates both NF-κB–driven inflammation and NRF2-mediated antioxidant responses, representing a potential therapeutic target for COPD–insomnia comorbidity." (PMID 41155519, 2025). "Future research should further explore the specific regulatory mechanisms of Berbamine on TNFAIP3, with the aim of providing novel therapeutic strategies for the co-morbid treatment of COPD and insomnia." (PMID 41155519, 2025). "The drug repositioning analysis identified several potential therapeutic compounds targeting TNFAIP3, a key hub gene shared by COPD and insomnia." (PMID 41155519, 2025). "This study revealed TNFAIP3’s dual role as a regulator of redox homeostasis and a suppressor of inflammatory signaling in COPD–insomnia comorbidity." (PMID 41155519, 2025). "Building on TNFAIP3’s mechanistic duality as a ubiquitin-editing hub for NF-κB (COPD pathogenesis) and circadian rhythm modulation (insomnia pathophysiology), its therapeutic exploitation warrants multi-modal drug engineering." (PMID 41155519, 2025). "This correlates with TNFAIP3’s role in regulating inflammation, suggesting Berbamine may exert effects through analogous mechanisms by influencing TNFAIP3 expression or function, potentially contributing to the treatment of COPD co-occurring with insomnia." (PMID 41155519, 2025).
Invasive ductal carcinoma (1 paper, 2026). "Invasive ductal carcinoma (IDC) exhibited the most prominent inhibition of TNFAIP3 at both mRNA and protein levels, with mRNA levels at 4.82 ± 0.35 log2(TPM + 1), representing a 1.9‐fold downregulation compared to normal, and a protein Z‐score of −0.92 ± 0.51." (PMID 41461391, 2026).
keratoconus (1 paper, 2024). A degenerative, structural disorder of the eye, characterized by a cone-shaped protrusion of the cornea. "In summary, these results indicate that TNFAIP3 may be a noteworthy gene associated with FDEGs, and it may have diagnostic utility in keratoconus." (PMID 38830963, 2024). "Consistent with the findings from a previous study (GSE77938), only the expression of TNFAIP3 (Tumor necrosis factor alpha induced protein 3) was significantly decreased in individuals with keratoconus compared to control subject." (PMID 38830963, 2024).
kidney injury (1 paper, 2022). Trauma to the kidney. "In conclusion, we demonstrated the role of PGC-1α in the regulation of the NLRP3 inflammasome activation via modulating mitochondrial dynamics and viability, and TNFAIP3 during kidney injury." (PMID 35013155, 2022).
leishmaniasis (1 paper, 2024). Infectious disease that is transmitted through the bite of hematophagous female phlebotomine sand flies. "The identification of hub genes of recruited datasets suggested that TNF, SOCS3, JUN, TNFAIP3, and CXCL9 may serve as potential infection biomarkers and could deserve value as prognostic biomarkers for leishmaniasis." (PMID 38839916, 2024).
liver fibrosis (1 paper, 2020). "Other E3 ligases that are moderately increased upon CCl4-induced liver fibrosis include Rnf4 (ring finger protein 4), Skp2 (S-phase kinase-associated protein 2), Ttc3 (tetratricopeptide repeat domain 3), and Tnfaip3 (tumor necrosis factor alpha-induced protein 3)." (PMID 33261190, 2020).
lymphopenia (1 paper, 2025). Reduction in the number of lymphocytes. "Similarly, RIPK1D138N mutation restored numbers of naive CD4+ and naive CD8+ T cells in Tnfaip3.Ikk2ΔTCD4 mice to near normal levels, confirming the dominant role of extrinsic cell death processes in the lymphopenia of Tnfaip3.Ikk2ΔTCD4 mice." (PMID 39327505, 2025). "We next asked whether the T lymphopenia in Tnfaip3.Ikk2ΔTCD4 mice was the result of a RIPK1 induced cell death process, by testing if kinase dead RIPK1D138N could reverse lymphopenia." (PMID 39327505, 2025).
mastitis (1 paper, 2023). Inflammation of breast tissue during lactation or postpartum due to an obstructed duct or infection. "LncRNAs such as LOC107133214, LOC104974443 and LOC101906793 can regulate the expression of inflammatory and cell death-related mRNAs such as IL-6, NFKB1 and TNFAIP3 and participate in the process of mastitis through NOD-like receptor, TNF, MAPK and other signaling pathways." (PMID 37845761, 2023).
meningococcal infection (1 paper, 2015). Infections with bacteria of the species neisseria meningitidis. "Meningococcal infection may interact with other components of NF-κB signaling pathway including IKK complex and/or A20/TNFAIP3 to attenuate the negative feedback loop mediated by IκB although cell lines and bacterial strains used in this study may account for these differences." (PMID 26241037, 2015).
metabolic syndrome (1 paper, 2012). A cluster of metabolic risk factors for CARDIOVASCULAR DISEASES and TYPE 2 DIABETES MELLITUS. "Receiver operating characteristic curve analysis revealed that IRAK3 (mean AUC, 95%CI: 0.63, 0.54–0.72, P<0.05), TNFAIP3 (0.65, 0.56–0.73, P<0.01), SOD2 (0.69, 0.60–0.77, P<0.001), and TNFα (0.71, 0.62–0.78, P<0.001) were associated with metabolic syndrome." (PMID 22272346, 2012).
metastatic diseases (1 paper, 2020). "Targeting the EVs-ITGBL1-CAFs-TNFAIP3-NF-κB signaling axis provides an attractive approach for treating metastatic diseases." (PMID 32139701, 2020).
myeloid leukemia (1 paper, 2014). A clonal proliferation of myeloid cells and their precursors in the bone marrow, peripheral blood, and spleen. "The expression levels of BMPR2, EP300, and TNFAIP3 mRNA in B-lymphoma cells were significantly higher than those of the myeloid leukemia cells (P<0.05)." (PMID 25364581, 2014). "Results indicate that the expression levels of BMPR2, EP300, and TNFAIP3 mRNA in myeloid leukemia cell lines were significantly lower than those of healthy people or B-malignant cell lines." (PMID 25364581, 2014). "Meanwhile, the expression levels of BMPR2, EP300, and TNFAIP3 mRNA in myeloid leukemia cells were significantly lower than those of healthy people." (PMID 25364581, 2014). "The expression levels of BMPR2, EP300, and TNFAIP3 mRNA in cell lines from myeloid leukemia were significantly lower than those in the cells from the healthy control (P<0.05)." (PMID 25364581, 2014). "The relative expression levels of BMPR2, EP300, and TNFAIP3 mRNA in cell lines from myeloid leukemia were significantly lower than those in the cells from the healthy people (P<0.05)." (PMID 25364581, 2014). "The median quantities of BMPR2, EP300, and TNFAIP3 expression in the myeloid leukemia cell lines are 0.10%, 0.56%, and 0.34%, respectively." (PMID 25364581, 2014). "BMPR2, EP300, and TNFAIP3 mRNA have been observed to be almost absent in myeloid leukemia cell lines." (PMID 25364581, 2014).
myositis (1 paper, 2018). "In large scale case-control studies in a Chinese Han population using candidate gene approach, CCL21, a myositis susceptibility gene in Caucasians, was found to associate with PM or PM-associated ILD, TNFAIP3 and IRF5 with myositis or myositis-associated ILD, and PLCL1 with DM and DM-associated ILD." (PMID 29854780, 2018).
Nasal polyposis (1 paper, 2023). Polypoidal masses arising mainly from the mucous membranes of the nose and paranasal sinuses. "Significantly, two SNPs (rs3757173 and rs5029938) in TNFAIP3 are associated with the susceptibility and severity of CRS and nasal polyposis." (PMID 37056760, 2023).
NK-T cell lymphoma (1 paper, 2021). "Additionally, a few previous studies have revealed that TNFAIP3 deletion is frequently found in cutaneous T-cell lymphoma (CTCL) and NK-T cell lymphoma (NKTCL)." (PMID 34526012, 2021).
nonalcoholic steatohepatitis (1 paper, 2023). "TNFAIP3 is known to promote the survival of CD4 T cells and to ameliorate the severity of nonalcoholic steatohepatitis." (PMID 38116005, 2023).
ovarian serous cystadenocarcinoma (1 paper, 2022). A malignant serous cystic epithelial neoplasm arising from the ovary. "Positive correlations were found between the mRNA levels of BCL3 with some of these target genes, such as TNFAIP3/A20, CCL2, CD274, and CXCL10, in brain lower grade glioma (LGG) and ovarian serous cystadenocarcinoma (OV) samples from TCGA database." (PMID 35990614, 2022).
pancreatic ductal adenocarcinoma (1 paper, 2021). An infiltrating adenocarcinoma that arises from the epithelial cells of the pancreas. "This study aimed to explore the significance and prognostic value of serum tumor-associated carbohydrate antigen 19-9 (CA19-9), D-dimer, and tumor necrosis factor alpha-induced protein 3 (TNFAIP3/A20) in patients with pancreatic ductal adenocarcinoma (PDAC)." (PMID 33578593, 2021). "The prognostic value of CA19-9, D-dimer, and TNFAIP3/A20 in patients with pancreatic ductal adenocarcinoma (PDAC) have not been thoroughly and extensively discussed." (PMID 33578593, 2021).
pulmonary hypertension (1 paper, 2025). Increased pressure within the pulmonary circulation due to lung or heart disorder. "Our previous research indicated that zinc regulates TNF‐alpha‐induced Protein 3 (A20/TNFAIP3) expression via the GPR39 receptor, providing protective effects against monocrotaline‐induced pulmonary hypertension in rats." (PMID 40026072, 2025).
pustular psoriasis (1 paper, 2025). "Loss-of-function or pathogenic variants in TNFAIP3 lead to dysregulated NF-κB activation, resulting in excessive inflammatory responses and autoimmune/autoinflammatory diseases such as pustular psoriasis." (PMID 41226818, 2025). "Thus, the combined effect of impaired transcriptional regulation (i.e., a mutation in RAD21) and enhanced inflammatory signaling (i.e., a mutation in TNFAIP3) may explain the coexistence of developmental abnormalities (CdLS) and inflammatory skin disease (pustular psoriasis) in the same patient." (PMID 41226818, 2025). "Histopathology confirmed pustular psoriasis, and clinical exome sequencing identified a heterozygous likely pathogenic variant in RAD21, associated with CdLS type 4 (CdLS4), and a heterozygous variant of uncertain significance in TNFAIP3, which is linked to familial autoinflammatory syndrome." (PMID 41226818, 2025).
retinal diseases (1 paper, 2017). "For example, the TNFAIP3 gene is highly expressed in human retina from the same ATSS as in mouse, the same is true for PLA2G5, a gene from the RetNet list for mapped loci and genes causing retinal diseases that has been implicated in recessive benign fleck retina." (PMID 28640837, 2017).
Shock (1 paper, 2019). The state in which profound and widespread reduction of effective tissue perfusion leads first to reversible, and then if prolonged, to irreversible cellular injury. "When the TNFAIP3, TNIP1, and MyD88 SNPs were included in the model, only the TNFAIP3 rs6920220 and TNIP1 rs3792783 SNPs were selected, and the predictive value significantly improved for discriminating between survivors and nonsurvivors shortly after septic shock onset (the first 28 days)." (PMID 30813592, 2019).
spondyloarthritis (1 paper, 2017). "Although multiple factors converge to regulate inflammatory cytokine production, we hypothesized that low TNFAIP3 may contribute to excessive cytokine production in spondyloarthritis." (PMID 28791018, 2017). "Mean TNFAIP3 was significantly lower in spondyloarthritis macrophages than controls (p = 0.0085)." (PMID 28791018, 2017). "Decreased expression of TNFAIP3 in AxSpA macrophages correlated with increased LPS-induced TNF-α, and thus, TNFAIP3 dysregulation may be a contributor to excessive inflammatory responses in spondyloarthritis subjects." (PMID 28791018, 2017).
T-cell leukemia (1 paper, 2017). A malignant disease of the T-lymphocytes in the bone marrow, thymus, and/or blood. "The association of alleles with higher TNFAIP3 levels has not been well described: there is only one report of a T-cell leukemia line bearing the rs5029948 variant with high TNFAIP3 expression level." (PMID 28791018, 2017).
thymoma (1 paper, 2017). A neoplasm arising from the epithelial cells of the thymus. "In summary, this study demonstrates that the rs7749323 in the TNFAIP3 gene is strongly associated with the LOMG (with positive AChR Ab but without thymoma)." (PMID 28514294, 2017). "In this study, the rs7749323 (locates in 3′ flanking region) of TNFAIP3 gene is found to have an associate with the LOMG (with positive AChR Ab and without thymoma) in the northern Han Chinese population." (PMID 28514294, 2017).
thyroid MALT lymphoma (1 paper, 2021). "We correlated TET2, TNFRSF14, CD274 and TNFAIP3 mutation AAF in thyroid MALT lymphoma in order to understand the sequence of their occurrence." (PMID 34021249, 2021). "We found frequent deleterious mutations of TET2 (86%), CD274 (53%), TNFRSF14 (53%), and TNFAIP3 (30%) in thyroid MALT lymphoma." (PMID 34021249, 2021). "TNFAIP3 was also frequently mutated in thyroid MALT lymphoma." (PMID 34021249, 2021).
Waldenstrom macroglobulinemia (1 paper, 2018). "Review of our genetic data on diffuse large B cell lymphoma (DLBCL) and Waldenstrom macroglobulinemia (WM), found that a large percentage of DLBCL and WM cases that have a MYD88 mutation also harbor a TNFAIP3 loss, 55% DLBCL and 28% of WM, respectively." (PMID 30301877, 2018).